RNU6-1032P (RNA, U6 small nuclear 1032, pseudogene)
Gene: Small nuclear RNA gene on chromosome 18 (22,647,582 to 22,647,688, forward strand). Ensembl gene ENSG00000206827.
Homologues: Orthologues: chimpanzee U6 (98% identical), macaque U6 (92% identical), guinea pig U6 (81% identical), dog U6 (78% identical), pig U6 (76% identical). Paralogues in human: RNU6-1152P (89% identical), RNU6-820P (89% identical), RNU6-19P (88% identical), RNU6-31P (88% identical), RNU6-35P (88% identical), RNU6-44P (88% identical), RNU6-589P (88% identical), RNU6-12P (87% identical), RNU6-13P (87% identical), RNU6-16P (87% identical), RNU6-211P (87% identical), RNU6-25P (87% identical), and 1288 more.